TRIM48 (tripartite motif containing 48)
Description:
E3 ubiquitin-protein ligase which promotes K48-linked polyubiquitination of protein methyltransferase PRMT1, leading to PRMT1 degradation. This suppresses methylation of the PRMT1 substrate MAP3K5/ASK1, promoting its activation and increasing MAP3K5-dependent cell death induced by oxidative stress. TRIM48-mediated ubiquitination of PRMT1 also suppresses methylation of FOXO1 by PRMT1, leading to inhibition of FOXO1 transcriptional activity. Additionally, it inhibits RIG-I-mediated antiviral signaling, functioning as an inducible negative feedback regulator of this pathway.
Synonyms: RNF101
Tractability: No criterion of Open Targets' tractability assessment is met for any kind of drug.
Gene: Protein-coding gene on chromosome 11 (55,262,155 to 55,271,114, forward strand). Ensembl gene ENSG00000150244.
Subcellular location: Cytoplasm, cytosol
Pathways (Reactome):
Immune System: Interferon gamma signaling
Gene Ontology:
Molecular function: protein binding; ubiquitin protein ligase activity; zinc ion binding
Biological process: proteasome-mediated ubiquitin-dependent protein catabolic process; innate immune response; regulation of gene expression
Cellular component: cytoplasm; cytosol
Genetic constraint (gnomAD): Loss-of-function variants: 26 observed, 22.8 expected, observed/expected ratio (o/e) 1.14, 90% interval 0.83 to 1.58. The synonymous counts are far from expectation, so gnomAD's model fits this gene poorly and the ratio says little. Missense variants: 317 observed, 229.49 expected, observed/expected ratio (o/e) 1.38, 90% interval 1.26 to 1.52. Synonymous variants: 121 observed, 77.49 expected, observed/expected ratio (o/e) 1.56, 90% interval 1.35 to 1.81.
Homologues: Paralogues in human: TRIM49D1 (88% identical), TRIM49D2 (88% identical), TRIM49 (80% identical), TRIM49C (80% identical), TRIM49B (79% identical), TRIM51 (70% identical), TRIM51G (70% identical), TRIM43 (57% identical), TRIM43B (56% identical), TRIM64B (44% identical), TRIM64 (44% identical), TRIM64C (43% identical), and 68 more.
Diseases named in the same sentence as TRIM48 in open-access papers:
TRIM48 is named in the same sentence as 5 diseases in open-access papers, as found by Europe PMC text mining. Sharing a sentence is not in itself a finding about the gene and the disease. The quoted sentences say what the papers report.
viral infection (1 paper, 2011). "TRIM proteins such as TRIM48 are thought to function during the cellular response to viral infection." (PMID 21291537, 2011).
infection (2 papers, 2023 to 2025). The state of being infected such as from the introduction of a foreign agent such as serum, vaccine, antigenic substance or organism. "Western Blot as well as qRT-PCR experiments further confirmed the expression of DUX4 and known DUX4-target genes TRIM48, TRIM49, ZSCAN4, ZSCAN5a, ZSCAN5d and RFPL4A upon HSV-1, HCMV and KSHV-infection 25 in different experimental settings." (PMID 38168299, 2023).
tumor (2 papers, 2023 to 2025). "TRIM48 is a human-specific tripartite motif (TRIM) family protein with E3 ubiquitin ligase activity that plays a significant role in the oxidative stress response and tumor suppression." (PMID 41096745, 2025).
cancer (1 paper, 2023). A tumor composed of atypical neoplastic, often pleomorphic cells that invade other tissues. "Based on these guidelines, TRIM21 and TRIM48 were identified as candidate cancer-relevant TRIM genes from our database screen." (PMID 37771771, 2023).
TRIM48 also shares sentences with these, for which no sentence is quoted: glioma (1 paper).